TNF (tumor necrosis factor)
Diseases named in the same sentence as TNF in open-access papers (continued):
Sharing a sentence is not in itself a finding about the gene and the disease.
periodontitis (continued). "Periodontitis patients exhibit increased blood CRP levels as well as proinflammatory cytokines such as TNF-α and interleukin-1 in their serum and gingival crevicular fluid (GCF)." (PMID 38021744, 2023). "Some recent reports, including ours from the ARIC dental study data, suggested elevated GCF or baseline GCF levels of IL-1β or TNF-α in T2DM individuals with chronic periodontitis/gingivitis." (PMID 37893143, 2023). "The present study investigated the role of TNF-α and Wnt signaling in the pathogenesis of destructive periodontitis." (PMID 37232780, 2023). "The majority of tissue destruction that occurs during periodontitis is attributed to IL-1β and TNF-α activity." (PMID 37102937, 2023). "No research has looked into the relationship between caspase-1 and TNF-α levels and periodontitis up until this point." (PMID 36794778, 2023). "In animal models of periodontitis, curcumin down-regulated the inflammatory cytokines interleukin-1β (IL-1β), interleukin-6 (IL-6) and tumor necrosis factor-α (TNF-α) and suppressed bone resorption by the suppression of RANKL expression." (PMID 37372983, 2023). "Caspase-1 and TNF-α salivary levels were increased in periodontitis patients compared to the healthy controls, and were positively correlated with clinical parameters." (PMID 36794778, 2023). "TNF-α, as a pro-inflammatory mediator, has been shown to have high serum levels in individuals with periodontitis, indicating its involvement in the pathologic process of periodontitis." (PMID 37798684, 2023). "In the synthetic (+)-terrein-treated mice, the expression of TNF-α mRNA in the periodontitis-induced area was significantly decreased in the PBS-treated mice (p = 0.005)." (PMID 36983482, 2023). "In mice with periodontitis, significantly increased level of IL‐1β, IL‐18, and TNF‐α was detected in gingival tissues." (PMID 37506160, 2023). "These disparities suggest that macrophages play a crucial role in stimulating TNF-α secretion during periodontitis, which is consistent with the previous findings that macrophages are a major source of TNF-α." (PMID 37232780, 2023). "Based on the results of the ROC curve, which was used for differentiating periodontal health from periodontitis, the results of AUC for TNF-α and caspase-1 were 0.978 and 0.998, respectively." (PMID 36794778, 2023). "A cross-sectional study found a positive correlation between gingival fluid TNF-α levels and blood pressure (p < 0.05), inducing a double inflammatory effect in patients with both periodontitis and hypertension." (PMID 37308938, 2023). "During periodontitis-related inflammation, osteocyte death, and upregulated expression of RANKL, SOST, IL-1β, and TNF-α disrupts bone homeostasis, causing alveolar bone loss." (PMID 37432277, 2023). "Another study that included 40 patients experiencing severe periodontitis showed that subjects assigned to TNF inhibitors showed improvements in BOP, PD, and CAL." (PMID 36845132, 2023). "Upon comparing the concentrations of TNFα between periodontitis and peri-implantitis, greater concentrations were noticed in the peri-implantitis group." (PMID 37232785, 2023). "PBMC cells from periodontitis subjects released higher levels of TNF‐a and IL‐6 than those from healthy subjects after Escherichia coli lipopolysaccharides stimulation." (PMID 37506160, 2023). "In this study, we aimed to clinically analyze the periodontal status and the cytokine levels of IL-1β, TNF-α, and IL-10 in older people and adults with periodontitis." (PMID 37623272, 2023). "gingivalis virulence factors arsenal, promoting an inflammatory microenvironment characterized by cytokine production (TNF-α, IL-1β, IL-6), prostaglandins, and metalloproteinases (MMPs) that foster the tissular destruction characteristic of periodontitis." (PMID 36897441, 2023).
periodontitis (continued). "These interactions can trigger the release of inflammatory molecules, such as interleukins and tumor necrosis factor (TNF), which can lead to alveolar bone loss and periodontitis." (PMID 37885557, 2023). "Levels of various pro-inflammatory cytokines including TNF-α are upregulated in the pulpitis-affected pulp tissue and periodontitis-affected alveolar bone." (PMID 36671503, 2023). "We anticipate that triangulation of evidence from genetics, observational research and clinical trials will elucidate the role of TNF inhibitors in periodontitis." (PMID 36845132, 2023). "Research efforts continue to unravel the impact of elevated pro-inflammatory cytokines like TNF-α on osteoclastogenesis in periodontitis." (PMID 37885557, 2023). "The present findings supported a previous discovery that periodontitis patients have significantly higher levels of salivary TNF-α." (PMID 36794778, 2023). "Considering the growing interest in the potential efficacy of anti-rheumatic agents (e.g., TNF inhibitors) in patients with periodontitis the present study aimed to test if blocking TNFR1 would reduce the risk of periodontitis using a drug target MR approach." (PMID 36845132, 2023). "We measured the concentrations of the inflammatory cytokines, TNF-α, and IL-6, in the serum of periodontitis-induced rats." (PMID 36677905, 2023). "HGFs stimulated with pathogens have been reported to upregulate the gene expression of the pro-inflammatory cytokines IL-6, IL-1β, IL-8, and TNF-α, which facilitates the inflammatory cascade in periodontitis." (PMID 37110385, 2023). "In the PBS-treated periodontitis mice, the serum TNF-α levels were significantly increased (p = 0.02)." (PMID 36983482, 2023). "In conclusion, our results demonstrated, through meta-analytic methods with 1,983 participants from 9 studies, that IL-6, nitric oxide, IL-1B, TNF-α and osteoprotegerin are among the most present biomarkers in patients with periodontitis." (PMID 37026605, 2023). "In RA and periodontitis, adaptive and innate immune cells promote the release of proinflammatory cytokines (TNF-α, IL-6, IL-17A, IL-1β, RANKL), which have an important role in establishing and maintaining inflammation." (PMID 37217496, 2023). "High concentrations of IL-1 and TNF-α were recorded 10 days after experimentally periodontitis was induced by injecting Escherichia coli lipopolysaccharide bilaterally into the palatal gingival tissue." (PMID 36840029, 2023). "The findings of this study contribute to our understanding of the complex interactions between TNF-α and Wnt signaling in periodontitis." (PMID 37232780, 2023). "Compared with the control group, periodontitis mice exhibited a significant increase in proinflammatory cytokine (IL-6, IL-1β, TNF-a, IFN-β) production (p < 0.05)." (PMID 37405166, 2023). "In the present study, we found that although the expression of TNF-α and the aberrant activated signaling were concurrent in the GEC and macrophages during periodontitis, the regulatory role of Wnt signaling on TNF-α was different in these two cell types." (PMID 37232780, 2023). "The interleukin-1 (IL-1) and IL-6 family members and tumor necrosis factor (TNF) are pro-inflammatory cytokines with key roles in the progression of periodontitis." (PMID 36899985, 2023). "Obese subjects with periodontitis are characterized by an increase in pro-inflammatory cytokines (IL-1β, IL-6, TNF), also in blood, and also in gingival fluid samples, compared to normo-weighted subjects with periodontitis." (PMID 37894804, 2023). "The aim of this study was to evaluate the salivary levels of caspase-1 and TNF-α and determine their accuracy in differentiating periodontitis patients from individuals with a healthy periodontium." (PMID 36794778, 2023). "This research aims to quantify 1,25(OH)2D and TNF levels in the bloodstreams of individuals afflicted with chronic periodontitis and those with healthy gums." (PMID 37885557, 2023).
periodontitis (continued). "First, IL-1β and TNF-α are elevated in periodontitis patients, and thus are considered representative inflammatory cytokines in this background." (PMID 37626627, 2023). "Increased concentration of TNFα observed in periodontitis correlates closely with tissue destruction and immune response." (PMID 36599866, 2023). "In the present study, it was found that there was an increase in TNF-α and IL-1β levels in rat gingiva after periodontitis induction and systemic celastrol application suppressed this increase." (PMID 38532834, 2023). "Our previous study found that 3 months of PG treatment elevates GCF levels of IL-6 and TNF-α in women with periodontitis." (PMID 37645411, 2023). "This study revealed a striking contrast: chronic periodontitis patients exhibited lower serum 1,25(OH)2D levels while concurrently displaying elevated serum TNF-α levels." (PMID 37885557, 2023). "After the data analysis, serum cytokine concentration was extracted from 11 periodontitis studies and the highest reported concentration for IL-1 β level was 114 pg/mL, whilst IL-6’s was 125.4 pg/mL, and TNF-α’s was 202.71 pg/mL." (PMID 37106750, 2023). "Periodontitis results in the formation of cytokines, most distinctively, tumor necrosis factor-alpha (TNF-α), interleukin (IL)-1, and IL-6/." (PMID 37102031, 2023). "As a result of caspase activation, the higher concentration of TNF-α seen in periodontitis closely correlates with the immune response and tissue destruction." (PMID 36794778, 2023). "In conclusion, this study demonstrated that synthetic (+)-terrein reduced osteoclast formation and alveolar bone resorption by interfering with TNF-α production in a mouse ligature-induced periodontitis model." (PMID 36983482, 2023). "After periodontitis, IL-34 promotes monocyte development toward macrophages, and macrophages secrete a series of cytokines, such as IL-6 and TNF-α, mediating the inflammatory response." (PMID 36879647, 2023). "Compared with 10% glucose, treatment with 0.1% stevioside reduced alveolar bone absorption and osteoclasts while decreasing IL-6, TNF-α, IL-1β, and P. gingivalis in the gingiva of periodontitis mice." (PMID 37563632, 2023). "The combination of NK357 with NK391 (NKc) additively decreased PG 16S rDNA levels and suppressed PG-induced periodontitis: the combination suppressed IL-6 and TNF-α expression and GP+LPS+ and NF-κB+CD11c+ cell populations in the periodontal tissue." (PMID 36904068, 2023). "For differentiating periodontal health and periodontitis, the area under the curve (AUC) values of TNF-α and caspase-1 were 0.978 and 0.998, while the proposed cut-off points were 128.163 pg/ml and 1.626 ng/ml, respectively." (PMID 36794778, 2023). "Serum 1,25(OH)2D and TNF values were compared between patients suffering from chronic periodontitis and healthy volunteers for the first time in this investigation." (PMID 37885557, 2023). "A number of retrospective studies demonstrated a correlation between polymorphisms of interleukins IL-1a, IL-1b, IL-1RN, IL-6, IL-10 as well as TNF-a and the incidence of periodontitis and peri-implant disease." (PMID 35819566, 2022). "TNF-α was also higher in smokers (in behavioral studies and research on Sjogren’s syndrome) and lower in periodontitis." (PMID 36005576, 2022). "For example, we need to identify the precise effects of MOP-EGCG on other markers of periodontitis such as TNF-α and IL-10." (PMID 36212598, 2022). "TNF-α is a major pro-inflammatory cytokine involved in the inflammatory phase of periodontitis, and is considered a major contributor to bone pathophysiology due to its stimulation of bone resorption." (PMID 36050950, 2022). "Although TNF-α is involved in both periodontitis and orthodontic tooth movement, the combined effect of TNF-α and mechanical strain on the inflammatory responses was never investigated in hPDLSCs to date." (PMID 34185172, 2022).
periodontitis (continued). "For example, in patients with periodontitis, Prevotella represented an enhanced ability to induce inflammatory mediators (IL-6, IL-8, and TNF-α)." (PMID 35938126, 2022). "We also observed that periodontitis induced by ligation with P. gingivalis can dramatically upregulate the TNF-α level in lung tissue under LF diet." (PMID 36060644, 2022). "The comparison of human gingival biopsies from periodontitis and healthy tissues have demonstrated distinct hypermethylation patterns of TIMP1 and TNFα promoter regions in periodontitis." (PMID 36291079, 2022). "Peripheral neutrophils from periodontitis patients release excess IL-1β, IL-8, IL-6, and tumor necrosis factor (TNF-α) when stimulated by periodontal pathogens." (PMID 36294367, 2022). "On the 7th day, TNF-α expression in all groups increased, indicating an inflammatory response due to periodontitis." (PMID 35178093, 2022). "The progression of periodontitis involves the release of prominent cytokines such as TNF-α, which is also involved at the early stage of inflammatory cascade, and IL-1 that are produced by the B-cell/plasma cell." (PMID 35903322, 2022). "This is characterized by production of numerous mediators like IL-1β, IL-6, IL-8, and TNF-α, which are also involved in the progression of periodontitis." (PMID 34185172, 2022). "TNF-α and IL-1β are the major secreted pro-inflammatory cytokines, that are important markers of periodontitis progression and severity." (PMID 36312752, 2022). "Periodontitis-related inflammatory cytokines, such as tumor necrosis factor (TNF) and IL-1β, produced from host cells exposed to the dental biofilm, produce a synergistic effect by increasing IL-6 synthesis resulting in increased Th17 cell activation." (PMID 35628348, 2022). "For example, patients with generalized chronic periodontitis treated with SRP and probiotic lozenges had significantly reduced levels of periodontal pathogenic red and orange complexes, tumor necrosis factor α (TNF-α), and IL1β." (PMID 35572634, 2022). "Inevitably, periodontitis leads to an increase of proinflammatory cytokines such as interleukin- (IL-) 1α, IL-1 β, tumor necrosis factor-alpha (TNFα), and IL-6." (PMID 35955456, 2022). "As TNF-α is an abundant pro-inflammatory cytokine that is upregulated in periodontitis, we examined the effect of TNF-α on peri-epithelial cell remodeling." (PMID 35137648, 2022). "In Pg-LPS-induced periodontitis, macrophages regulate the inflammatory response by producing a variety of proinflammatory mediators such as TNF-α, IL-6, and IL-1β." (PMID 35340409, 2022). "In periodontitis, TNF is a main contributor to periodontal damage in periodontal tissue destruction." (PMID 34405311, 2022). "It was found that TNF-α had a significant relationship in patients with periodontitis and type 2 diabetes who received treatment." (PMID 35016229, 2022). "In a study conducted on rats, TNF-α levels decreased in those animals which experienced periodontitis and received DM and dietary treatment." (PMID 35016229, 2022). "Then we examined if PPARα has a similar TNFα regulating effect on immune cells under periodontitis conditions." (PMID 35830121, 2022). "As the dose of DhHP-6 increased, the levels of TNF-α and IL-1β were significantly lower than those in the periodontitis group." (PMID 36546940, 2022). "In parallel, we detected elevated levels of TRAP+ osteoclasts, TNF-α and IL-1β in mice receiving a periodontitis patient donated microbiome." (PMID 35958276, 2022). "In models of periodontitis, fucoxanthin was shown to inhibit the promotion of osteoclast differentiation and reduce TNF, IL-1β, and IL-6 levels in blood." (PMID 36501023, 2022). "Th1 cells are involved in the first phase of periodontitis; they release pro-inflammatory cytokines, such as IL-1, TNF, and IL-6." (PMID 36362030, 2022).
periodontitis (continued). "Starting with a report that the methylation of CpG sites in the promoter of IFNγ was significantly higher in the gingiva of periodontitis patients, methylation of TLR2 promoter, TNF-α promoter, and others were reported to be associated with periodontitis." (PMID 36294882, 2022). "Studies have shown that patients with periodontitis have higher circulating white blood cells, acute-phase proteins (CRPs), tumor necrosis factor (TNF), interleukins (IL), and ROS." (PMID 35625570, 2022). "The treatment group with the administration of VCO gel in periodontitis-induced Wistar rats experienced a significant increase in TNF-α expression, compared to other groups." (PMID 35178093, 2022). "Compared to their young counterparts, old mice suffer frequent spontaneous periodontitis, and the expression of IL-1β and TNF-α in the gingiva is significantly elevated." (PMID 36275775, 2022). "The similar cytokine profile of periodontitis and RA includes increased levels of TNF-α, IL-1, MMPs and PEG2, and low levels of tissue inhibitors of metalloproteinases (TIMP)." (PMID 35371044, 2022). "Proinflammatory cytokines IL-1β, IL-6, and TNF-α are present in osteoclast precursor cells and mature osteoclasts, and it mediates bone resorption in periodontitis." (PMID 35757444, 2022). "TNF-α is the core inflammatory cytokine during periodontitis, which is suitable for establishment of inflammatory microenvironment." (PMID 36199627, 2022). "In a rat model of experimental periodontitis, treatment with fucoxanthin led to a decrease in blood levels of TNF-α and IL-6." (PMID 35327570, 2022). "Significant increases in serum levels of TNF-α, and IL-6 were reported in maternal animals with ligature-induced periodontitis, as well as in offspring exposed to maternal periodontitis in the pregnancy and lactation period." (PMID 35269617, 2022). "Concerning oral dysbiosis, resveratrol can reduce P. gingivalis LPS-induced TNF-α, IL-6 and IL-1β production in human periodontal ligament cells aggravating destructive tissue processes in periodontitis and promoting systemic inflammation." (PMID 35327570, 2022). "By day 15, the periodontitis-induced cfDNA and TNF-α increase in both saliva and serum was reduced by both G3@SeHANs and PAMAM-G3, with the nanoparticle more effective than the soluble counterpart." (PMID 36207325, 2022). "In fact, human periodontal ligament cells (HPDL cells) collected from patients with chronic periodontitis had higher levels of inflammatory cytokines, including IL-6, TNF-α, and HMGB-1, than HDPL cells collected from healthy individuals." (PMID 36163018, 2022). "Salivary levels of miR-1246 in patients with chronic periodontitis were positively correlated with the levels of IL-1β, IL-6, IL-17, TNF-α, MMP-1, MMP-8, TIMP-1, PLI, GI, PD, and AL (P < 0.05)." (PMID 35942384, 2022). "The association between tumor necrosis factor-alpha (TNF-α −308G/A, −238G/A, −863C/A, −1031T/C, and −857C/T) polymorphism and either chronic or aggressive periodontitis susceptibility is conflicting." (PMID 35454140, 2022). "Previously, by using a rat model of LPS-induced periodontitis, we confirmed that administration of EA into the gingival sulcus markedly reduced immunoexpression of TNF-α at the junctional epithelium." (PMID 36794024, 2022). "Previously, by using the rat model of LPS-induced periodontitis, we confirmed that EA treatment markedly reduced immunoexpression of TNF-α at the junctional epithelium." (PMID 36794024, 2022). "Especially, P. gingivalis-LPS is a strong virulence factor in periodontitis and induces cytokine secretion (TNF-α, IL-6, and MCP-1) and inflammatory responses via TLRs." (PMID 35564380, 2022). "TNF-α levels were higher in the serum of patients with chronic periodontitis than those in control subjects with minimally inflamed periodontal tissues." (PMID 35845957, 2022).